GFAP (glial fibrillary acidic protein)
Diseases named in the same sentence as GFAP in open-access papers (continued):
Sharing a sentence is not in itself a finding about the gene and the disease.
Alexander disease (continued). "For instance, Alexander disease mutant GFAP activates a c-Jun N-terminal kinase (JNK) stress response that blocks proteasome activity." (PMID 26378915, 2015). "We find that GFAP levels are consistently elevated in the CSF of patients with Alexander disease, but only occasionally and modestly elevated in blood." (PMID 26478912, 2015). "The accumulation of GFAP that is found in Alexander disease results in part from increased synthesis, as mRNA levels are increased and there is a spontaneous increase in the activity of the GFAP promoter." (PMID 26378915, 2015). "In conclusion, lithium has the potential to decrease GFAP levels in Alexander disease, but with a narrow therapeutic window separating efficacy and toxicity." (PMID 26378915, 2015). "In conclusion, we show that lithium decreases GFAP in a mouse model of Alexander disease, possibly through transcriptional mechanisms involving STAT3." (PMID 26378915, 2015). "Previous studies have shown that lithium can increase autophagy through the IMPase pathway, and increasing autophagy with rapamycin decreases GFAP levels in astrocytoma cells expressing Alexander disease mutant GFAP." (PMID 26378915, 2015). "Nevertheless overexpression of GFAP also can be lethal and lead to the discovery of Alexander disease, a severe neurodegenerative disorder." (PMID 25793004, 2015). "Astrocytes are the major producers of GFAP, and Alexander disease astrocytes present Rosenthal fibers accumulation and increased levels of GFAP." (PMID 25426477, 2014). "GFAP, encoding glial fibrillary acidic protein, linked to expression of the glutamate transporter Glt1 (SLC1A2) in Alexander disease, was also over-expressed in affected animals (FC 2.60)." (PMID 23782433, 2013). "Their endings differed from GFAP fragments described in Alzheimer’s and Alexander disease." (PMID 42032706, 2026). "In addition to the full-length protein, SMI-21 and 2.2B10 detected GFAP degradation products in samples from Alexander disease mice and humans." (PMID 38891912, 2024). "Finally, by using an astrocyte‐related disease, Alexander disease (AxD) patient‐derived iPSCs, we detected disease phenotypes, including glial fibrillary acidic protein (GFAP)‐aggregates, and gene expression changes." (PMID 38509731, 2024). "A different Alexander disease model overexpressing wildtype human GFAP ranked 13th." (PMID 38236817, 2024). "Promising results are being shown in studies on reducing GFAP levels in Alexander disease, which may lead to the first clinical trials." (PMID 38920997, 2024). "Mutations in glial fibrillary acidic protein (GFAP) in astrocytes, as seen in Alexander disease, trigger a significant adverse impact on the efficiency of astrocytic mitochondrial transfer though they fail to alter the number or properties of intracellular mitochondria in astrocytes." (PMID 39133904, 2024). "Growth factors, cytokines, chemokines and antioxidant enzymes are upregulated initially in astrocytes when they become reactive, and mutant glial fibrillary acidic protein (GFAP), a signature of astrocyte reactivity, in Alexander disease dysregulates autophagy." (PMID 36829434, 2023). "The leukodystrophy Alexander disease (AxD) is a rare condition affecting myelin sheath and is most often caused by gain-of-function mutations in glial fibrillary acidic protein (GFAP) which lead to the overproduction and toxic accumulation of GFAP in protein inclusions called Rosenthal fibres." (PMID 35067193, 2022). "Alexander’s disease (AxD) is a rare, usually relentlessly progressive disorder of astroglial cells in the central nervous system related to mutations in the gene encoding the type III intermediate filament protein, glial fibrillary acidic protein (GFAP)." (PMID 34950024, 2021). "One way or another, GFAP levels are elevated in Alexander disease." (PMID 31838996, 2019).
Alexander disease (continued). "With the present state of knowledge about GFAP and Alexander disease, we must accept the possibility that disease reflects a combination of both gain and loss of different functions, although we would argue that ultimately it is the gain-of-function that dominates." (PMID 31838996, 2019). "Young patients with Alexander disease had high levels of GFAP breakdown products and caspase-6." (PMID 31682229, 2019). "Furthermore, GFAP in Cerebrospinal Fluid (CSF) serves as a potential biomarker of Alexander disease that is comparable between mouse models and human patients." (PMID 30996271, 2019). "GFAP levels are indeed elevated in Alexander disease, and one important question is why?" (PMID 31838996, 2019). "The exact form of GFAP that promotes F-actin stabilization in Alexander disease is unclear." (PMID 29765022, 2018). "The insolubility of GFAP in advanced AD and Alexander’s disease could have deleterious effects in astrocyte biology by both overwhelming their protein degradation systems, autophagy and proteasome, and restricting their range of migration and process motion." (PMID 29922147, 2018). "To determine whether GFAP promotes F-actin stabilization through spectraplakin, we took advantage of the Drosophila model of Alexander disease." (PMID 29765022, 2018). "Alexander disease (AxD) is an astrogliopathy that predominantly affects the white matter of the central nervous system (CNS), and is caused by a mutation in the gene encoding the glial fibrillary acidic protein (GFAP), an intermediate filament primarily expressed in astrocytes and ependymal cells." (PMID 28882119, 2017). "In the case of Alexander disease, the autosomal dominantly inherited leukodystrophy is caused by mutations of GFAP (glial fibrillary acidic protein) for which there is no ortholog in flies." (PMID 26935104, 2016). "Variants in GFAP are associated with Alexander disease, and although our patient showed several features of Alexander disease, he had an atypical progression of disease with no signs of regression and a less severe presentation of symptoms." (PMID 27648269, 2016). "Due to its reported effects on autophagy, STAT3, and GFAP, we sought to test whether lithium could decrease GFAP levels in a mouse model of Alexander disease." (PMID 26378915, 2015). "Indeed, GFAP increases are consistently found in Alexander disease, both when measured in brain parenchyma as well as in CSF." (PMID 26378915, 2015). "Here we tested whether lithium treatment would decrease levels of GFAP in a mouse model of Alexander disease." (PMID 26378915, 2015). "Alexander’s disease is characterized by atypical myelination, developmental delay, and macroencephaly, with astrocytes exhibiting Rosenthal fiber accumulation, and abnormally high expression of GFAP." (PMID 26793073, 2015). "Indeed, based largely on cell culture models, autophagy appears to be naturally increased in Alexander disease patients, and autophagy contributes to the degradation of GFAP." (PMID 26378915, 2015). "Experimental studies have demonstrated that these fibers can originate from either expression of mutant GFAP or over-expression of wild-type GFAP and that elevation in total levels of GFAP may be a critical element in the pathogenesis of Alexander disease." (PMID 24798087, 2015). "Protoplasmic astrocytes in patients with Alexander disease, a primary disorder of astrocytes, caused by heterozygous mutations in GFAP (glial fibrillary acidic protein), convert to reactive cells that lost their bushy-like morphology and become multinucleated and hypertrophic." (PMID 25999819, 2015). "Adult-onset Alexander disease (AxD) is the late-onset form of GFAP-related leukodystrophy, usually manifesting after adolescence with progressive spastic paraparesis and variable bulbar or cerebellar features." (PMID 41303265, 2025).
Alexander disease (continued). "Alexander disease (ALXDRD; OMIM#203450) is a rare disorder caused by variants in the gene encoding the Glial Fibrillary Acidic Protein (GFAP) (HGNC:4235)." (PMID 39420046, 2024). "First identified in 1949, Alexander disease (AxD) constitutes a form of leukodystrophy affecting the CNS white matter, marked by myelin sheath degeneration due to a defect in the Glial Fibrillary Acidic Protein (GFAP) gene." (PMID 38390857, 2024). "90% of currently-identified Alexander disease (AxD) cases are characterized by cellular gain-of-function glial fibroblast acidic protein (GFAP) aggregates, also known as Rosenthal fibers, in the astrocytes." (PMID 36077104, 2022). "Development of a peripheral demyelinating neuropathy was reported in an 8-year-old patient with Alexander disease, but apart from this case, there is currently no compelling evidence that GFAP accumulation or overexpression contributes to or causes PNS degeneration." (PMID 33481951, 2021). "Alexander’s disease (AxD, MIM#203450) is a rare, usually relentlessly progressive genetic disorder of astroglial cells in the central nervous system related to heterozygous mutations in the gene encoding the type III intermediate filament protein, glial fibrillary acidic protein (GFAP)." (PMID 34950024, 2021). "Likewise, in Alexander disease, a rare neurodegenerative disease characterized by cytoplasmic proteinaceous aggregates containing GFAP, the proteolytic fragmentation of GFAP has been related to disease severity and has been suggested to be central in the pathogenesis." (PMID 31693684, 2019). "Mutations in the astrocyte intermediate filament glial fibrillary acidicprotein (GFAP) result in Alexander disease (AxD)." (PMID 30355500, 2018). "Based on previous reports that lithium increases the autophagy pathway for protein degradation, and other studies where lithium treatment was associated with a decrease in GFAP itself, we tested whether lithium would decrease GFAP accumulation in a mouse model of Alexander disease." (PMID 26378915, 2015). "Interestingly, some of the BMAA-induced enriched proteins in the histopathologically altered area, such as plectin, GFAP, vimentin, Hsp 27, and ubiquitin, are known to form complex astrocytic inclusions, the so-called Rosenthal fibers, in the neurodegenerative disorder Alexander disease." (PMID 24798087, 2015). "In Alexander disease (AxD) the presence of mutant glial fibrillary acidic protein (GFAP), the major intermediate filament of astrocytes, triggers protein aggregation, with marked induction of a stress response mediated by the transcription factor, Nrf2." (PMID 22693571, 2012). "The coexisting overexpression of GFAP and CRYAB has been shown for Rosenthal fibers in Alexander’s disease, chronic glial scars, and low- and high-grade fibrillar astrocytomas." (PMID 35360493, 2022). "For Alexander disease, application of the ASO approach to treatment will require better understanding of how closely the GFAP levels in CSF and blood reflect those in the brain and spinal cord, so that each individual’s response to treatment can be assessed in the least invasive way possible." (PMID 31838996, 2019). "Alexander disease (ALX) is a rare neurological disorder characterized by white matter degeneration and cytoplasmic inclusions in astrocytes called Rosenthal fibers, labeled by antibodies against glial fibrillary acidic protein (GFAP)." (PMID 20359319, 2010). "Interestingly, some RNAs including PLP1 (SPG2), MAG (SPG75), and GFAP (Alexander disease) are expressed in none of the cell types studied here." (PMID 33072739, 2020). "Overexpression of GFAP might contribute to astrocyte dysfunction in AxD as was shown in initial studies of overexpressing wild type GFAP in transgenic mice, which resulted in the formation of Rosenthal fibers indistinguishable from those found in Alexander disease patients." (PMID 27402089, 2016).
Alexander disease (continued). "Presence of high-molecular-mass forms of GFAP in both children (p = 0.0393) and non-significantly in adults with ASD is novel and has been reported to occur in Alexander disease previously due to oxidative stress and altered redox signaling, conditions that occur in ASD brain." (PMID 40779003, 2025).
glioblastoma (178 papers, 1977 to 2026). The most malignant astrocytic tumor (WHO grade IV). "The aim of this study was to test the diagnostic value of a GFAP point-of-care device to differentiate glioblastoma from other brain tumors." (PMID 41762323, 2026). "CONCLUSION: GFAP measurements using a point-of-care device indicate glioblastoma with high diagnostic accuracy." (PMID 41762323, 2026). "Next, to shed light on the molecular mechanisms underlying glioblastoma development in the GFAP-Cre; KrasG12D; APCL/+; p53L/L mouse model, our study examined the expression of various markers." (PMID 38473403, 2024). "This technique utilizes specific antibodies to detect and visualize the expression of proteins associated with glioblastoma, such as GFAP (glial fibrillary acidic protein), Ki-67, and IDH1 (isocitrate dehydrogenase 1)." (PMID 39338377, 2024). "In glioblastoma stem cells, the expression levels of proteins associated with differentiation, such as glial fibrillary acidic protein (GFAP), Notch1 and Shh, were increased by β-elemene in vitro and in vivo." (PMID 35488254, 2022). "The cytomorphological parameters defined for the primary glioblastoma cell cultures were analyzed in dependence of the GFAP expression strength to find possible associations." (PMID 33251771, 2021). "Short term maintenance of five out of ten analyzed GB cases in a form of neurospheres provided cultures of GFAP-positive cells, with only slight percentage of glioblastoma-associated stromal cells (GASCs; positive for the expression of α-SMA)." (PMID 31521143, 2019). "The latest WHO classification for CNS tumors which will be released in spring 2021 still recognizes glioblastomas with primitive neuronal component, and loss of GFAP expression, MYC/MYCN gene amplification, elevated Ki67 proliferation index and increased cerebrospinal fluid dissemination." (PMID 33876327, 2021). "However, GFAP expression associates with the CL subtype of glioblastoma, and although GFAP remains the most used astrocyte marker, it is also regarded as a marker for reactive astrocytes and expressed by the neural progenitor cells." (PMID 33986188, 2021). "However, when performing a biopsy procedure or a surgical resection of a glioblastoma, the high expression of GFAPδ, an alternative splice variant of GFAP, could predict the invasiveness and the increased risk for tumor recurrence." (PMID 35372061, 2022). "GFAP is one of the well-known diagnostic markers for glioblastoma, but the proteins forming clusters close to those of GFAP may relate to the pathogenesis of glioblastoma." (PMID 32238824, 2020). "It is reported that via interfering the binding of miR-139 and 3′UTR, variant G allele of rs11558961 that reduced GFAP expression contributes to low GFAP expression, and further inhibits the chemo-resistance and metastasis of glioblastoma (GBM) cells." (PMID 31049031, 2019). "A GFAP plasma concentration of > 1000 pg/ml was indicative of glioblastoma with a specificity of 95% and a positive predictive value (PPV) of 82%." (PMID 41762323, 2026). "Glial fibrillary acidic protein (GFAP) has been studied as a blood biomarker for glioblastoma using conventional immunoassays." (PMID 41762323, 2026). "GFAP plasma levels were significantly higher in patients with glioblastoma (n = 37; median 610 pg/mL [interquartile range 263.5–1877.5]) compared to other tumors (n = 64; 81.5 pg/mL [40.3–197.3]; p < 0.001)." (PMID 41762323, 2026). "Immunohistochemical staining was conducted on paraffin-embedded human glioblastoma tissue slices to demonstrate representative P2X7R expression in tumour tissue (GFAP+) obtained from 5 glioblastoma patients." (PMID 41034696, 2025). "As a rule, recurrent glioblastomas are characterized by diffuse pronounced staining for GFAP; therefore, GFAP-positive EVs can be present in the blood plasma in large quantities." (PMID 39996852, 2025).
glioblastoma (continued). "We also performed double-labeling with GFAP, a well-established marker of astrocytomas and glioblastomas in rodent models." (PMID 41226489, 2025). "Using immunohistopathology, we also detected FX in glial cells of glioblastoma tissue identified by the glial cell marker GFAP." (PMID 40149552, 2025). "GFAP is a protein that is classically used to identify malignancies of glial origin, such as astrocytoma and glioblastoma." (PMID 39996852, 2025). "To confirm the cell origin, we showed that primary glioblastoma cultures express intermediate filament GFAP and microtubule III β-tubulin using confocal microscopy." (PMID 40553392, 2025). "In one study, patients with glioblastoma multiforme and high levels of circulating GFAP + monocytes had a worse prognosis." (PMID 40457397, 2025). "One such model, the GFAP-Cre; KrasG12D; p53L/L mouse model, has been engineered to mimic the genetic alterations observed in human glioblastoma." (PMID 38473403, 2024). "Their identification as glioblastoma cell lines was solidified by confirming their immunopositivity for the glial marker GFAP." (PMID 38473403, 2024). "At the same time, the co-expression of the integrin αvβ3, vascular endothelium marker CD31 and GFAP were observed on neovascular endothelial cells in glioblastoma area." (PMID 38647690, 2024). "GFAP positivity serves as a valuable marker in identifying components of glioblastoma, with the positive rate and depth of cell staining being linked to the differentiation of astrocytomas." (PMID 39158355, 2024). "As our optimized combination strategy decreased PI3K/Akt and neuregulin signaling (a consequence of PKC inhibition), reduced glioblastoma signaling was predicted corresponding to the reduced expression of GFAP." (PMID 38319732, 2024). "The ICC and IF results showed positive staining for GFAP confirming the glioblastoma phenotype of the patient-derived glioblastoma cultured cells." (PMID 39153914, 2024). "Immunohistochemical studies demonstrated the colocalisation of B1R with GFAP, a marker for glioblastoma, in the area where accumulated radioactivity was observed in the autoradiogram with [111In]In-DOTA-Ahx-R954." (PMID 39065752, 2024). "The human glioblastoma U373 MG stable line, which also expresses GFAP, was used as a positive control." (PMID 37389023, 2023). "Following treatment, cells were fixed, stained and the number of DAPI + cells for U251 cells, and GFAP + /DAPI + cells for primary glioblastoma cultures were quantified via fluorescence microscopy." (PMID 37225786, 2023). "There is level B3 evidence for serum YKL-4032 in glioblastoma as well as GFAP and NfL33 in various brain tumours for monitoring radiographic disease status." (PMID 36745974, 2023). "Conventional glioblastomas are immunoreactive for GFAP, however, there is an inconsistent staining pattern of GFAP and, sometimes, a complete loss of expression in several of the histological subtypes is observed." (PMID 37239289, 2023). "It was shown that GFAP expression in glioblastoma tumors is increased in comparison to other brain cancer types." (PMID 36662405, 2023). "GFAP is a glial fibrillary acidic protein that is a promising biomarker and therapeutic target in glioblastoma and other cancers; however, its role in prostate cancer has not been fully explored." (PMID 37746266, 2023). "A recent meta-analysis also showed that GFAP levels measured from serum can be used to identify glioblastoma, but further studies are needed since currently the sensitivity of this method is still poor." (PMID 35372061, 2022). "Considering these contradictory findings regarding the role of the overall expression of GFAP as a prognostic factor for glioblastoma patients, it is necessary to evaluate the expression of the GFAP isoforms." (PMID 35372061, 2022).